SNORA71A (small nucleolar RNA, H/ACA box 71A)
Synonyms: U71a; RNU71A
Gene: Small nucleolar RNA gene on chromosome 20 (38,427,309 to 38,427,442, reverse strand). Ensembl gene ENSG00000225091.
Gene Ontology:
Biological process: RNA processing
Cellular component: nucleolus
Homologues: Orthologues: chimpanzee SNORA71 (97% identical), macaque SNORA71 (91% identical), guinea pig SNORA71 (84% identical), guinea pig SNORA71 (83% identical), rat Snora71a (73% identical), mouse Gm55920 (64% identical), mouse Gm26003 (63% identical). Paralogues in human: SNORA71D (84% identical), SNORA71C (84% identical), SNORA60 (79% identical), SNORA71E (74% identical), SNORA71 (73% identical), SNORA71 (69% identical), SNORA71 (68% identical).
Diseases named in the same sentence as SNORA71A in open-access papers:
SNORA71A is named in the same sentence as 3 diseases in open-access papers, as found by Europe PMC text mining. Sharing a sentence is not in itself a finding about the gene and the disease. The quoted sentences say what the papers report.
glioblastoma (2 papers, 2015 to 2017). The most malignant astrocytic tumor (WHO grade IV). "Among the ten most upregulated genes, five (SNORA20, SNORA71A, SNORA23, SNORA3, SNORA68) were recently found to be downregulated by HOXA10 in LN18 glioblastoma cells." (PMID 26362268, 2015).
non-small cell lung carcinoma (1 paper, 2022). A group of at least three distinct histological types of lung cancer, including non-small cell squamous cell carcinoma, adenocarcinoma, and large cell carcinoma. "For instance, SNORA71A functions as an oncogene in non-small cell lung cancer." (PMID 35821006, 2022).
tumor (1 paper, 2022). "Similarly, all studied SNHGs are involved in EMT through activation of various athways including Notch-1, but in vivo experiments reveal a more crucial role in tumor growth and metastasis for SNHG1, SNHG3, SNHG5, SNHG12, and SNORA71A." (PMID 36139687, 2022).